BCL2 (BCL2 apoptosis regulator)
Diseases named in the same sentence as BCL2 in open-access papers (continued):
Sharing a sentence is not in itself a finding about the gene and the disease.
cardiac hypertrophy (20 papers, 2014 to 2026). "Rat bone marrow-MSC (BM-MSC-EVs) have also been tested in an in vitro model of cardiac hypertrophy on H9c2 cells, resulting in the downregulation of Bax and Caspase-3 and upregulation of Bcl-2, overall reducing apoptosis." (PMID 38892376, 2024). "There are studies showing that Bcl-2 is involved in cardiac hypertrophy as a key downstream effector of the PI3K-Akt signaling pathway." (PMID 38334841, 2024). "It is indicated that Bcl-2 is of great possibility to be a therapeutic target for the clinical management of cardiac hypertrophy." (PMID 33778070, 2021). "In conclusion, these data indicate that Bcl-2 is involved in cardiac hypertrophy as a central downstream effector of PI3K-Akt signaling pathway, suggesting a potential therapeutic target for the clinical management of cardiac hypertrophy." (PMID 33778070, 2021). "In our study of TAC mice treated with inhibitors in vivo, we found that no matter LY294002, an inhibitor of the PI3K/AKT signaling pathway, or Venetoclax, a selective Bcl-2 inhibitor, protected against cardiac hypertrophy." (PMID 33778070, 2021). "In conclusion, these data indicate that Bcl-2 is involved in cardiac hypertrophy as a key downstream effector of PI3K-Akt signaling pathway, suggesting a potential therapeutic target for the clinical management of cardiac hypertrophy." (PMID 33778070, 2021). "The expression levels of autophagy-related proteins (ATG7 and LC3A/B) were significantly reduced in aged WT and Y-Sesn2 KO hearts during cardiac hypertrophy, while levels of apoptosis-related proteins (BCL2 and BAX) increased." (PMID 32863202, 2020). "In conclusion, increased BP, reduced NO level, increased activity of LDH, and imbalance of Bcl-2 and caspase-3 increase myocardial hypertrophy, which exacerbates cardiac dysfunction." (PMID 29234388, 2017). "Moreover, TQ inhibits cardiomyocyte ferroptosis and apoptosis by downregulating PTGS2, Bax, and upregulating GPX4, Bcl-2, thereby alleviating cardiac hypertrophy and dysfunction." (PMID 41614426, 2026). "HSP70 is protective inanti-apoptosis as it acts on different links of the apoptosis signaling pathway.Upregulation of HSP70 can promote Bcl-2 expression, reduce Bax expression, andincrease the ratio of Bcl-2/Bax, thereby inhibiting cardiomyocyte apoptosis anddelaying cardiac hypertrophy." (PMID 39484135, 2024). "Elevated Bcl-2 expression mitigates cardiac hypertrophy induced bylow ambient temperatures in vivo." (PMID 39484135, 2024). "Furthermore, no matter LY294002, an inhibitor of the PI3K/AKT signaling pathway, or Venetoclax, a selective Bcl-2 inhibitor, protected against cardiac hypertrophy." (PMID 33778070, 2021). "Furthermore, a previous study has proved that up-regulated Bcl-2 could attenuate low ambient temperature-induced myocardial hypertrophy in vivo." (PMID 28513772, 2017). "In conclusion, the present study evidences that Bcl-2 works as the central downstream effector of PI3K-Akt signaling pathway to keep cardiomyocyte survival, resulting in cardiac hypertrophy." (PMID 33778070, 2021). "Additionally, the levels of the molecular markers of cardiac hypertrophy, fibrosis, and apoptosis (such as MyHC, Col-1, MMP-9, TGF-β, Bax, Bcl-2, and Caspase-3) were decreased by PD98059 or LY317615." (PMID 34395424, 2021). "The mRNA levels of myocardial hypertrophy marker genes, including atrial natriuretic factor (ANF), matrix metalloproteinase (MMP)-9 and MMP-13, were detected by qRT-PCR, and the expressions of apoptosis-related proteins (Bcl-2 and Bax) were measured by western blotting." (PMID 28513772, 2017).
COVID-19 (20 papers, 2020 to 2025). A disease caused by infection with severe acute respiratory syndrome coronavirus 2. "Compared with the healthy group, COVID-19 patient group displayed the significantly lower expression level of BCL2, but significantly higher expression levels of MMP9, ICAM1, and TLR4." (PMID 41411324, 2025). "Similar to the EGFR state observed in mild COVID-19, we also detected altered expression of Bcl2, AKT1, and MAPK8." (PMID 39502570, 2024). "Further, severe COVID-19 patients exhibited reduced expression of the pro-survival factor BcL2 and the emergence of a TCF1-low, caspase 3 + T-cell population, indicating increased cell death." (PMID 38702425, 2024). "Regarding the regulation of apoptosis molecules, caspase-3, caspase-9, Bcl-2, and Bax are essential factors in alleviating LC, PF, and COVID-19." (PMID 37007037, 2023). "At the same time, BCL2 in the peripheral blood of COVID-19 patients was negatively correlated with the severity of the disease." (PMID 37113134, 2023). "Clinical studies have found that serum concentrations of BCL2 in COVID-19 patients correlate with patient prognosis, with high BCL2 concentrations predicting a better prognosis." (PMID 35677450, 2022). "Bcl-2 inhibitors exert potent antiviral activities against COVID-19." (PMID 40300201, 2025). "Most used targeted drugs were Bruton-kinase inhibitors (BKIs) (N= 201, 55%), anti-CD20 other than rituximab (N=61, 16%), BCL2 inhibitors (N=33, 9%) and lenalidomide (N=28, 8%).Only 16.2% of the patients were vaccinated with 2 or more doses of vaccine at the onset of COVID-19." (PMID 36276116, 2022). "BCL-2 and Jak 1/2 inhibitors could be repurposed as immunomodulators for not only HIV-1 and COVID-19, but other viruses that upregulate BCL-2 anti-apoptotic proteins." (PMID 36569952, 2022). "As the Jak STAT pathway is an upstream regulator of BCL-2 expression, a potential connection between BCL-2 and severe COVID-19 may exist but needs further investigation." (PMID 36569952, 2022). "Furthermore, increasing soluble Fas and B-cell CLL/lymphoma-2 (Bcl2) levels in COVID-19 patients raises the fatality rate in COVID-19 individuals." (PMID 35200677, 2022). "Specifically, patients treated with anti-CD20, BTKi, and BCL2-inhibitors were seroconversion failure after COVID-19 vaccination have been described, could be considered to receive early treatment with antivirals and monoclonal antibodies or pre-exposure prophylaxis." (PMID 36276116, 2022). "Similarly, activation of COX2 and HIF-1α in COVID-19 has been shown to upregulate the antiapoptotic antiproliferative microenvironment (BCL2, BNIP3) and M1 immune system {nuclear factor kappa B (NFKB), Egl-9 family hypoxia inducible factor 3 (EGLN3), CXCL8, TNF-α, and IL-6 }." (PMID 36671699, 2022). "Then, five important IADEGs (AXL, MKI67, CDKN3, BCL2 and PTGS2) for severe COVID-19 were screened by random forest analysis." (PMID 37113134, 2023). "Among, AXL, BCL2 and PTGS2 were clustered as a group with high expression in the normal sample and low expression in the COVID-19 sample." (PMID 37113134, 2023). "We screened the genes based on their degree values and identified RELA, BCL2, JUN, FOS, and MAPK1 as possible core target genes for puerarin in treatment of COVID-19/COAD." (PMID 35677450, 2022). "In summary, the activation of IGFR-I and enhanced NOTCH signaling, coupled with altered expression of Bcl2, AKT1, and MAPK8 in severe COVID-19 may lead to an environment that favors cell survival and proliferation." (PMID 39502570, 2024).
COVID-19 (continued). "By using Cytoscape software to visualize the degree of each gene in the PPI network, we found that RELA, BCL2, JUN, FOS, and MAPK1 had the highest degree, suggesting that the five genes might be core targets of puerarin in COVID-19/COAD comorbidity." (PMID 35677450, 2022). "Therefore, AXL, MKI67, CDKN3, BCL2 and PTGS2 might be key markers for occurrence and development of severe COVID-19." (PMID 37113134, 2023). "Furthermore, AXL, MKI67, CDKN3, BCL2 and PTGS2 as a marker combination could be used as potential markers to identify severe COVID-19 patients." (PMID 37113134, 2023).
retinoblastoma (20 papers, 2008 to 2025). A malignant tumor that originates in the nuclear layer of the retina. "In summary, our study identifies a regulatory axis NRMT/CENPA/Myc/Bcl2 implicated in the resistance to CDDP in retinoblastoma cells, which contributes to the comprehensive understanding of molecules and pathways that control CDDP-induced apoptosis." (PMID 35013138, 2022). "The results of RT-qPCR and western blot analysis illustrated that Bcl2 expression increased in the retinoblastoma tissues compared with that in the normal tissues." (PMID 35013138, 2022). "The uHRF1-mediated PI3K/Akt signaling pathway downregulates the bcl-2/Bax expression ratio and promotes caspase-9 expression, which can inhibit the proliferation of retinoblastoma cells and promote apoptosis." (PMID 35656341, 2022). "B cell lymphoma-2 (Bcl2), an anti-apoptotic protein, was reported to facilitate cell proliferation and restrain apoptosis of retinoblastoma cells." (PMID 35013138, 2022). "In human retinoblastoma, the expression of anti-apoptotic Bcl-2 is significantly related to poor differentiation and strong invasiveness, and the lack of Bax expression is related to choroidal infiltration and lymph node metastasis." (PMID 35991559, 2022). "In this study, we found that inhibition of PAX6 in human retinoblastoma cell lines led to a low apoptotic rate which was supported by the changes in the levels of apoptosis-related proteins (Bcl-2 and BAX)." (PMID 24939714, 2014). "Over expression of antiapoptotic protein bcl2 has been observed in retinoblastoma leading to decreased chemo-sensitivity." (PMID 22470431, 2012). "Importantly, aberrant expression of the NRTM/CENPA/Bcl2 axis developed in cisplatin (CDDP) resistance of retinoblastoma cells." (PMID 36012427, 2022). "Additionally, GRg5 promotes apoptosis in retinoblastoma cells by inhibiting the Akt signaling pathway and thereby downregulates Bcl-2 expression." (PMID 35885925, 2022). "Bcl2 was illustrated to prevent apoptosis of retinoblastoma cells." (PMID 35013138, 2022). "Furthermore, CENPA induces the transcription of Myc and elevates the expression of Bcl2 in retinoblastoma cells." (PMID 36012427, 2022). "Notably, overexpression of bcl-2 protein in retinoblastoma, confer drug resistance and make the disease more aggressive." (PMID 22470431, 2012). "In addition to LRP and MRP-1 in eliciting drug resistance in retinoblastoma, antiapoptotic protein bcl2 and cell survival protein NFκB also play significant role in multidrug resistance of retinoblastoma." (PMID 22470431, 2012). "In a word, Myc could upregulate Bcl2 expression in retinoblastoma cells." (PMID 35013138, 2022). "Hence, Myc impeded the chemosensitivity of retinoblastoma cells by upregulating Bcl2." (PMID 35013138, 2022). "In human retinoblastoma (WERI-Rb-1 and Y-79) cells, lupeol diminished cell viability and triggered apoptosis, evidenced by elevated Bax levels and reduced Bcl-2, Ki67, and survivin levels." (PMID 40417209, 2025). "Meanwhile, hsa-miR-486-3p inhibits retinoblastoma cell growth by regulating the target gene ECM1, and hsa-miR-7641 regulates the apoptotic marker caspase-9 and anti-apoptotic marker BCL2, establishing them as oncogenic miRNAs." (PMID 37233676, 2023). "Important mediators of the insulin pathway such as Akt, BCL-2 antagonist of cell death (BAD), FOXO1, and FASN were found to be phosphorylated in both retina and retinoblastoma tissues." (PMID 29914080, 2018). "Our results demonstrated that STAT3 activation induced up-regulation of BCL2, BCL2L1, BIRC5, and MMP9 genes in retinoblastoma cells." (PMID 25359779, 2014). "At last, our in vivo experimental data confirmed the downregulation of CENPA/Myc/Bcl2 by NRMT silencing, which possibly could be the mechanism responsible for the enhanced chemosensitivity of retinoblastoma cells." (PMID 35013138, 2022).
retinoblastoma (continued). "Furthermore, target genes of STAT3 including BCL2, BCL2L1, BIRC5, and MMP9 are up-regulated in retinoblastoma cells compared to other retinal constituent cells." (PMID 25359779, 2014). "In both retinoblastoma cell lines, the levels of Bcl-2, CDK1 and PCNA were significantly upregulated in the PAX6 inhibition study groups than in negative GFP-control groups (Bcl-2, t=−5.90, P<0.05 and t=−4.86, P<0.05, resp." (PMID 24939714, 2014).
schizophrenia (20 papers, 2009 to 2026). A major psychotic disorder characterized by abnormalities in the perception or expression of reality. "The networks we built for schizophrenia risk miRNAs imply the disease-associated deregulation of BCL2/BAX and the resultant enhancement in cell susceptibility to apoptosis, which possibly involves an increase in the production of reactive oxygen species." (PMID 32194626, 2020). "It must be emphasized that reduced Bcl-2 mRNA expression and activity is associated with severe neurodevelopmental disorders such as Down syndrome and schizophrenia." (PMID 30857240, 2019). "Increased expression of hsa-miR-208b-3p, hsa-miR-494-5p, and hsa-miR-208a-3p may augment susceptibility to schizophrenia by simultaneously conferring susceptibility to apoptosis and altering neural processing and connectivity through the suppression of BCL2 and CACNA1C, respectively." (PMID 32194626, 2020). "It is consistent with other data showing that clozapine and olanzapine enhanced the expression of the antiapoptotic protein Bcl-2 in an animal model of schizophrenia." (PMID 41010622, 2025). "An investigation of brain tissue from schizophrenia patients identified a decrease in Bcl-2 levels (around 25% when compared to normal) in the middle temporal gyrus (MTG)." (PMID 38256307, 2023). "The anti-apoptotic membrane-bound protein Bcl2 is decreased in the cortical of schizophrenia, and Bax/Bcl2 ratio is significantly higher in schizophrenia patients." (PMID 36769337, 2023). "As expected, we found a significant positive correlation between XBP1 and BCL-2 in schizophrenia (R2 = 0.58)." (PMID 37376599, 2023). "Our results suggest significant relationships between the increased expression of apoptosis genes (Bcl2, Birc6, Bax, Casp3, and Casp9) in peripheral blood lymphocytes and immune system dysregulation in patients with schizophrenia." (PMID 35566680, 2022). "A population of anti-psychotic medicine-naive first-episode schizophrenia patients show higher caspase-3 activity and lower BCL2 expression." (PMID 25191698, 2014). "Among the proteins that are related to apoptosis, the level of Bcl-2 is reduced by 25% in the middle temporal gyrus in patients with schizophrenia as compared with controls." (PMID 20040103, 2009). "Moreover, antipsychotic treatment increased the cortical expression of antiapoptotic factor, Bcl-2, in patients suffering from schizophrenia." (PMID 41010622, 2025). "Furthermore, an increased ratio of pro-apoptotic BAX to anti-apoptotic BCL-2 protein in the dorsolateral prefrontal cortex (DLPFC) from patients compared with controls suggests a bias favoring cell death processes in schizophrenia." (PMID 22545112, 2012). "A high Bax/Bcl-2 ratio is also detected in the neurons and glia of the temporal cortex of patients with schizophrenia, which suggests that pro-apoptotic stimuli might be more likely to lead to the uncontrolled release of cytochrome c in these cells than in normal cells." (PMID 20040103, 2009). "Increased protein and mRNA levels of BAX relative to BCL2 have been found in the temporal cortex and PFC of patients with schizophrenia." (PMID 41567988, 2026). "Taken together, ATF6, BCL-2, and ERVW-1 displayed a significant correlation with XBP1 in schizophrenia." (PMID 37376599, 2023).
schizophrenia (continued). "Subsequent research indicated that the UPR gene called XBP1 had a positive correlation with ATF6, BCL-2, and ERVW-1 in individuals with schizophrenia using Spearman correlation analysis." (PMID 37376599, 2023). "Although it is still unknown whether or not the apoptosis is a cause or a result of schizophrenia, the previous study suggest that antipsychotic treatment can raise the anti-apoptotic factor Bcl-2 level in the schizophrenic cortexes of treated subjects compared to antipsychotic-naive subjects." (PMID 21779358, 2011). "For BCL2, the connections to schizophrenia are at the level of cellular processes rather than genetic ones." (PMID 32194626, 2020). "The increased levels of the anti-apoptotic/pro–cell survival markers MCL1 and BCL2 and unchanged levels of the pro–cell death markers BID and BAX suggest a balance toward activated cell survival mechanisms in the midbrains of individuals with schizophrenia and bipolar disorder." (PMID 41567988, 2026). "As previous studies have demonstrated decreased Bcl-2 levels, increased Bax/Bcl-2 ratio and unaltered Caspase-3, it was proposed that increased vulnerability to pro-apoptotic stimuli occurred in the early stages of schizophrenia, but not in chronic schizophrenia." (PMID 29795286, 2018).